NLRP3 (NLR family pyrin domain containing 3)
Diseases named in the same sentence as NLRP3 in open-access papers (continued):
Sharing a sentence is not in itself a finding about the gene and the disease.
acute respiratory distress syndrome (44 papers, 2020 to 2026). Progressive and life-threatening pulmonary distress in the absence of an underlying pulmonary condition, usually following major trauma or surgery. "Autopsy findings and animal models have consistently affirmed that the aberrant expression of NLRP3 inflammasomes significantly contributes to the pathophysiological mechanisms underlying acute respiratory distress syndrome (ARDS)." (PMID 38399989, 2024). "Feng and colleagues showed that miR-223 crucially inhibits the activity of the NLRP3 inflammasome to alleviate the acute lung injury/acute respiratory distress syndrome (ALI/ARDS) induced by mitochondrial damage-associated molecular patterns (DAMPs)." (PMID 39125761, 2024). "Several studies showed that the NLRP3 inflammasome and IL-1β are implicated in the inflammatory response during lung injury and acute respiratory distress syndrome (ARDS)." (PMID 34209586, 2021). "When calcium sensitive receptors (CaSRs) are activated in alveolar macrophages (AMs), they trigger pyroptosis of AM cells, initiate the NLRP3 inflammasome pathway, and enhance the mortality rate of acute respiratory distress syndrome." (PMID 39355841, 2024). "Many studies report that the NLRP3 inflammasome is involved in respiratory diseases such as acute lung injury (ALI)—acute respiratory distress syndrome (ARDS) caused by pathogenic microorganisms such as influenza A virus, Pseudomonas aeruginosa, and Staphylococcus aureus." (PMID 38068879, 2023). "Another study found that metformin inhibits the activation of the NLRP3 inflammasome and attenuates acute respiratory distress syndrome by targeting the electron transport chain complex 1 independent of the AMPK or NF-kB pathways." (PMID 37928155, 2023). "Given NLRP3-mediated inflammation and cytokine storm are associated with disease severity in IAV and SARS-CoV-2 infection, suppressing NLRP3 inflammasome hyperactivation and cytokine storm may alleviate acute respiratory distress syndrome (ARDS)." (PMID 36110852, 2022). "Release of mtDNA and activation of the AIM2/NLRP3 inflammasome have been suggested to play a role in acute respiratory distress syndrome (ARDS) and acute lung injury (ALI)." (PMID 40264103, 2025). "Additionally, it can also be used as an anti-inflammatory drug to improve acute respiratory distress syndrome (ARDS) by regulating the NLRP3 inflammasome and pyroptosis." (PMID 40626309, 2025). "This study discusses the anti-inflammatory mechanism of Yiqi Huayu Jiedu decoction (YQHYJD) and studies the intervening effect of YQHYJD on the inflammatory cytokines in acute respiratory distress syndrome (ARDS) rats by inhibiting the TLR4/NLRP3 signal pathway." (PMID 35222667, 2022). "Accumulating evidence suggests that NLRP3-mediated alveolar macrophage (AM) pyroptosis and subsequent high mobility group box protein 1 (HMGB1) secretion play significant roles in the pathogenesis of acute respiratory distress syndrome (ARDS)." (PMID 40599023, 2025). "Therefore, the hypercapnia resulting from lung-protective ventilatory strategies used in acute respiratory distress syndrome (ARDS) patients may lead to neuroinflammation and cognitive impairment via a microglial NLRP3/IL-1β-dependent mechanism." (PMID 37189617, 2023). "In summary, our study confirmed that SYQP induced bidirectional immunity and ameliorated LPS-induced acute respiratory distress syndrome in mice through TLR2/TLR4-NF-κB, NLRP3/caspase and JAK/STAT signaling pathways, which provided a theoretical basis for further use of SYQP." (PMID 35370633, 2022). "Further, the activation of NLRP3 inflammasome was detected in AEC II from patients with acute respiratory distress syndrome (ARDS) and LPS-induced ALI mice." (PMID 35734175, 2022).
acute respiratory distress syndrome (continued). "In LPS and polyinosinic:polycytidylic acid (POLY I:C)-induced acute lung injury (ALI)/acute respiratory distress syndrome (ARDS) models, CGA counteracts the inflammatory and oxidative stress in human airway epithelial cells and in BALB/c mice through targeting the TLR4/TLR3/NLRP3 inflammasome axis." (PMID 38612964, 2024). "Metformin, as the first-line medication for the treatment of diabetes, inhibited NLRP3 inflammasome activation and IL-1β production in cultured and alveolar macrophages, thus attenuating LPS and SARS-CoV-2-induced acute respiratory distress syndrome (ARDS)." (PMID 35847986, 2022). "Interestingly, acute respiratory distress syndrome (ARDS) was observed as a characteristic feature of the rapid progression of severe lung injury among those that died from severe COVID-19 infection, and one of its pathological features is activation of the NLRP3 inflammatory pathway." (PMID 34522180, 2021). "NLRP3 inflammasome overactivation produces excessive IL-1β and downstream cytokines such as IL-6 and TNF-α, are also observed in acute respiratory distress syndrome (ARDS), ventilator induced lung injury (VILI), and disseminated intravascular coagulation (DIC)." (PMID 34150848, 2021).
amyotrophic lateral sclerosis (44 papers, 2016 to 2025). Amyotrophic lateral sclerosis (ALS) is a neurodegenerative disease characterized by progressive muscular paralysis reflecting degeneration of motor neurons in the primary motor cortex, corticospinal tracts, brainstem and spinal cord. "Their pathological potential is significantly determined by the NOD-like receptor 3 (NLRP3) inflammasome, which is implicated in many neurodegenerative diseases, such as Alzheimer’s and Parkinson’s disease or amyotrophic lateral sclerosis (ALS)." (PMID 38409076, 2024). "To date, a pathogenic role of the NLRP3 inflammasome has been shown in several neurodegenerative diseases including AD, MS and amyotrophic lateral sclerosis (ALS)." (PMID 28337127, 2017). "Like other neurological disorders, amyotrophic lateral sclerosis (ALS) involves the NLRP3 inflammasome activation-mediated inflammatory pathway in response to pathogenic proteins, such as β-amyloid and α-synuclein." (PMID 40643515, 2025). "In this review, we summarize the available knowledge about the NLRP3 inflammasome in neuromuscular diseases that affect the peripheral nervous system and amyotrophic lateral sclerosis, which affects the central nervous system." (PMID 34199845, 2021). "Activation of Nlrp3 inflammasome has been observed in a variety of neurodegenerative diseases, including AD and amyotrophic lateral sclerosis (ALS)." (PMID 29274035, 2018). "In addition, numerous researches have revealed the role of NLRP3 inflammasome in many other neurodegenerative diseases such as frontotemporal dementia, amyotrophic lateral sclerosis (ALS), Huntington's disease, and multiple sclerosis (MS)." (PMID 27652274, 2016). "Here, we discuss the impact of irisin on the NLRP3 inflammasome pathway, as well as the potential role of this pathway in Parkinson’s disease (PD), AD, and amyotrophic lateral sclerosis (ALS), and the therapies that target the NLRP3 inflammasome." (PMID 39683782, 2024). "Since NLRP3 inflammasome plays a pivotal role in several neurodegenerative disorders, we hypothesized that levels of inflammasome components could help in diagnosis or prognosis of amyotrophic lateral sclerosis (ALS)." (PMID 33802349, 2021). "In a model of amyotrophic lateral sclerosis (ALS) caused by C9orf72 gene mutations, the pathogenic poly-dipeptide GA50 directly binds to and inhibits SQOR, leading to excessive NLRP3 inflammasome activation in microglia and consequent mitochondrial dysfunction." (PMID 41210256, 2025). "Furthermore, in the SOD1 (G93A) transgenic mice model of amyotrophic lateral sclerosis (ALS), NLRP3 activation was predominantly detected in degenerating neurons of the anterodorsal thalamic nucleus." (PMID 33328988, 2020). "Similarly, other research teams have reported increases in the expression and activity of NLRP3, IL-1β, IL-18 and caspase-1 in plaques of MS patients and the tissues of amyotrophic lateral sclerosis (ALS) (or motor neurone disease) patients." (PMID 29052145, 2018). "The proinflammatory NLRP3 contributes to the pathology of a broad spectrum of neurological diseases, such as stroke, traumatic injury, and neurodegenerative diseases, including Alzheimer and amyotrophic lateral sclerosis (ALS)." (PMID 29403486, 2017). "Similarly, activation of the NLRP3 inflammasome and subsequent GSDMD cleavage have been observed in the microglia of amyotrophic lateral sclerosis (ALS) patients and in Parkinson’s disease (PD) mouse models." (PMID 39994107, 2025). "Moreover, astroglia can express NLRP3 inflammasome and IL-1β under certain conditions, such as in SOD1 mouse model of amyotrophic lateral sclerosis (ALS) and human sporadic ALS patients, and amyloid β1–42-stimulated murine astrocytes." (PMID 32070376, 2020).
epilepsy (44 papers, 2014 to 2025). A brain disorder characterized by episodes of abnormally increased neuronal discharge resulting in transient episodes of sensory or motor neurological dysfunction, or psychic dysfunction. "The inhibition of NLRP3 inflammasome activation ameliorates epilepsy and neuropsychiatric disorders of multiple causes." (PMID 40806374, 2025). "As a potential target for the treatment of epileptogenesis, NLRP3 inflammasome has been demonstrated to be associated with neuroinflammation and epilepsy." (PMID 31417409, 2019). "Not only is the NLRP3 inflammasome the best studied inflammasome, it is also implicated in inflammation and epilepsy." (PMID 31417409, 2019). "Recent research suggest that increased activity of NLRP3 contributes to the development and progression of epilepsy; hence, inhibiting the activity of NLRP3 may reduce inflammation-caused epileptic injuries and potentially improve symptoms." (PMID 38892264, 2024). "Therefore, the goal of this review is to highlight the role of chronic inflammation with a specific focus on the NLRP3 inflammasome in the neurodegenerative damage associated with epilepsy progression." (PMID 37893198, 2023). "Complementarily, we studied NLRP3 inflammasome-associated transcript patterns in epileptogenic hippocampi with different damage patterns of pharmacoresistant TLE patients that had undergone epilepsy surgery for seizure relief." (PMID 35972937, 2022). "Besides, the neuronal loss induced by the pentylenetetrazol-induced epilepsy model was demonstrated to be significantly inhibited in NLRP3 knockout mice." (PMID 34112082, 2021). "The NLRP3 inflammasome is associated with neuroinflammation and epilepsy." (PMID 34421582, 2021). "Recently, the NLRP3 inflammasome, a key constituent of the inflammasome complex, has been implicated in the sterile inflammatory response via the processing of caspase-1, IL-18, and IL-1β in the setting of epilepsy and some other neurological diseases." (PMID 32005256, 2020). "NLRP3 inhibitors, a potential new class of drugs, might have fewer side effects and be more effective in a larger number of patients, and could target the underlying causes of epilepsy." (PMID 38892264, 2024). "The correlation between NLRP3 levels and the severity of seizures highlights the potential diagnostic and prognostic value of these markers in clinical settings, shedding light on future therapeutic strategies aimed at mitigating the detrimental effects of neuroinflammation in epilepsy." (PMID 37893198, 2023). "A large body of research evidence suggests that the activation of NLRP3 in epilepsy models is closely related to the inward flow of calcium ion." (PMID 40217546, 2025). "Given the critical role of neuroinflammation in epilepsy and neuronal damage, we further investigated the involvement of the NLRP3 inflammasome, a key mediator of inflammatory responses." (PMID 41246312, 2025). "GPR120 regulates neuroinflammation through the NLRP3/Caspase-1/IL-1β signaling pathway in an epilepsy animal model." (PMID 40075143, 2025). "In a mouse model of pilocarpine-induced epilepsy, four studies consistently show that inflammation is enhanced through NLRP3, caspase 1, ASC, gasdermin D, IL-1β, and IL-18 pathways." (PMID 40217546, 2025). "Numerous preclinical studies have confirmed that the NLRP3 inflammasome pathway is closely related to the development of epilepsy." (PMID 40075143, 2025). "Combined treatment with valproic acid and furosemide significantly reduces the protein expression levels of ASC and NLRP3 and decreases the severity of epilepsy in rats." (PMID 40075143, 2025). "ZNF883-induced USP47 expression suppressed NLRP3 ubiquitination and promoted epilepsy by sponging miR-138-5p." (PMID 40307577, 2025). "In this review, we discuss the advances in understanding the regulatory mechanisms of NLRP3 activation as well as progress made, and challenges faced in the development of NLRP3 inhibitors for the treatment of epilepsy." (PMID 38892264, 2024).
epilepsy (continued). "Wu and colleagues reported that the number of NLRP3+ cells in the temporal lobe cortical tissues of refractory epilepsy patients was significantly higher than the control group." (PMID 38892264, 2024). "NLRP3 activation has been shown to influence the pathophysiology of Parkinson’s disease, multiple sclerosis, and epilepsy." (PMID 38662166, 2024). "Several clinical trials are underway, exploring the efficacy and safety of NLRP3 inhibitors in patients with chronic, drug-resistant epilepsy." (PMID 38892264, 2024). "Consistent with our findings, liraglutide reduced IL-1β and TNF-α levels in a rat model of PTZ-induced epilepsy, highlighting the NLRP3 inflammasome complex as a potential target for antiepileptogenic treatments." (PMID 39457518, 2024). "Here, we indicated endothelial IL-1R1 is involved in neuroinflammation, facilitating epilepsy progress via Nrf2/HO-1/NLRP3." (PMID 38087170, 2024). "An increase in NLRP3 activity has been shown in the brains of individuals with epilepsy and in animal models of epilepsy." (PMID 38892264, 2024). "Recently, the expression of NLRP1 and NLRP3 mRNAs was significantly increased in the animal model of epilepsy induced by the intrahippocampal injection of KA compared to controls." (PMID 38892264, 2024). "Lines reported that the activation of NLRP1 and NLRP3 inflammasomes is involved in the development of epilepsy." (PMID 37365625, 2023). "Based on an extensive review of the literature on the role of NLRP3-dependent inflammation in epilepsy, in this review we discuss our current understanding of the connection between NLRP3 inflammasome activation and progressive neurodegeneration in epilepsy." (PMID 37893198, 2023). "In animal and clinical epilepsy-related research, increased levels of the NLRP3 inflammasome and neuroinflammatory cytokines have been detected in hippocampal tissues." (PMID 35456948, 2022). "Since IL-1β and IL-18 are signaling pathways downstream of NLRP3, our data can indirectly prove that GPR120, as a ligand of NLRP3, regulates the activation of NLRP3 and induces neuroinflammation in epilepsy." (PMID 35624482, 2022). "In a Sprague–Dawley rat model of kainic acid (KA)-induced epilepsy, curcumin suppressed KA-evoked epileptic syndromes via inhibition of NLRP3 inflammasome activation, opening up a potentially salutary effect in epilepsy." (PMID 34443594, 2021). "Remarkably, in vivo injection of NLRP3 small interfering RNAs displayed neuroprotective effects in rats following amygdala kindling-induced epilepsy." (PMID 33066071, 2020). "The role of NLRP3 inflammasome in the development of epilepsy was confirmed by a recent study showing that children with febrile seizures have higher serum levels of IL-1β, correlated to NLRP3 upregulation in PBMCs, as compared to healthy controls." (PMID 33066071, 2020). "Activation of the NLRP3 inflammasome has been detected during epilepsy, and knockdown of NLRP3 or caspase-1 decreased IL-1β and IL-16 levels and provided neuroprotection against SE-associated neuronal damage." (PMID 31097691, 2019). "NLRP1 and NLRP3 are the two best characterized members of inflammasomes and their activation during epilepsy has been documented in both basic and clinical researches." (PMID 28503575, 2017). "In a mouse model of pilocarpine-induced epilepsy, activation of the transcriptional repressor Rev-erbalpha decreased NLRP3 expression in the brain, reduced NLRP3-mediated inflammatory vesicle activation, and inhibited astrocyte proliferation and neuronal death." (PMID 40217546, 2025). "Pharmacological or genetic blockade of NLRP3 may improve the progression of epilepsy by alleviating neuroinflammation." (PMID 40075143, 2025). "Moreover, elevated levels of USP47 are correlated with NLRP3 inflammasome activation and the progression of epilepsy." (PMID 40307577, 2025). "NLRP3 inhibitors as potential epilepsy therapeutics at pre-clinical stages." (PMID 38892264, 2024).